IL10 (interleukin 10)
Diseases named in the same sentence as IL10 in open-access papers (continued):
Sharing a sentence is not in itself a finding about the gene and the disease.
colitis (continued). "Whereas, rCsCP ameliorated the acute colitis might through activating innate immunity, downregulating the expression of pro-inflammatory factors (IL-12, IL-23r and IL-7), and promoting the production of anti-inflammatory factors (IL-10, IL-4 and IL-13)." (PMID 36084127, 2022). "Similarly, taxon-based analysis of the microbiota revealed that levels of the Helicobacter genus inversely correlated with severe colitis in IL-10-deficient mice, demonstrating disease is not dependent on co-colonisation with this pathobiont." (PMID 36012618, 2022). "Our current results indicated that rCsCP or CsCA might down-regulate the inflammatory responses of colitis mice via elevating Treg cells in both the spleens and MLNs, inducing the release of Th2 cytokines (IL-10, IL-4 and IL-13), and restraining the production of IL-1β and IL-2 cytokines in serum." (PMID 36084127, 2022). "Additionally, in colitis it has been observed that S. cerevisiae may exhibit regulatory effects on the host, notably by inducing higher IL-10 production from dendritic cells compared to Candida." (PMID 35472144, 2022). "Administration of 25.2 g/kg BW of FBPE decreased the IFN-γ, TNF-α and IL-4 levels, while enhancing the IL-10 level, and significantly inhibited the abnormally decreased IgG (Model: 13.25 mg/mL, HD: 14.06 mg/mL), showing a reversal effect on the Th1/Th2 levels in colitis." (PMID 35564016, 2022). "Therefore, IL-10−/− mice serve as models of C. jejuni induced colitis, autoantibody elicitation and sub-clinical inflammation in the peripheral nervous system but are an insufficient model for studying severe clinical changes associated with GBS such as paralysis and respiratory insufficiency." (PMID 35442154, 2022). "Moreover, in certain circumstances, for example, IL-10 knockout mice, Akkermansia could promote colitis and MetS by destroying the mucus layer." (PMID 35463645, 2022). "Loss of IL-10 production by Foxp3+ Tregs has been correlated with disease progression in a NOD model of type 1 diabetes, and disruption of IL-10 expression in Foxp3+ Tregs led to spontaneous colitis and augmented immune-response related inflammation in the skin and lungs of mice." (PMID 36466912, 2022). "Furthermore, this study demonstrated the colitogenic capacity of A parvulum in an Il10−/− colitis model, with the increased expression of the chemokine (C‐X‐C motif) ligand 1 (Cxcl1) and Il17 in the gut, compared with controls, which was mitigated by the administration of the H2S scavenger bismuth." (PMID 35244953, 2022). "Furthermore, treatment with NK151, NK173, NK175, or their (3:1:1) mix suppressed IS-induced colitis: they suppressed colonic IL-1β and IL-6 expression and the NF-κB+CD11c+ cell number along with the fecal endotoxin level, meanwhile increasing the IL-10 cytokine level in the colon." (PMID 35631220, 2022). "Therefore, Pygo2 knockdown in Il‐10−/− mice can promote PPARγ expression and induce the differentiation of adipocytes, while also inhibiting mesenteric fat inflammation, thereby inhibiting colitis." (PMID 35707871, 2022). "However, in this study, IL-10 was necessary for ET to alleviate colitis." (PMID 33717186, 2021). "In the DSS-induced colitis mouse model, Firmicutes and Bifidobacterium were reported to be positively correlated with IL-10 (P < 0.05), Enterobacteriaceae was positively correlated with IL-1β (P < 0.05), and Turicibacter was negatively correlated with IL-10 (P < 0.05)." (PMID 33748287, 2021). "Furthermore, various strains of Bifidobacteria have been shown to exert an anti-inflammatory effect through induction of intestinal IL-10 and treatment with Bifidobacterium bifidum was shown to partially protect mice from Th1-driven inflammation in a chemically induced model of colitis." (PMID 34103031, 2021). "Therefore, our observations indicate that defects in p40phox may enhance iNOS expression and NO production, which may lead to alterations in IL‐10 production and colitis development." (PMID 33780601, 2021).
colitis (continued). "In contrast, germ-free IL10-deficient mice did not develop colitis after norovirus infection." (PMID 34836426, 2021). "We demonstrated that olaparib improved TNBS-induced colitis in mice, reduced histological damage of the colon, diminished the number and length of the ulcers, inhibited proinflammatory cytokine production (IL-1β, IL-6), but it enhanced the level of anti-inflammatory cytokine IL-10." (PMID 34567413, 2021). "Additionally, Bifidobacterium has been reported to alleviate DSS-induced colitis by suppressing the IL-17A response and prevent intestinal inflammation through the induction of intestinal IL-10-producing Tr1 cells, further confirming the protective role of Bifidobacterium in colitis." (PMID 33748287, 2021). "Additionally, the carcinogenic agent, azoxymethane, induced colon tumors in colitis-susceptible interleukin (IL)-10 knockout mice colonized with certain commensal bacteria but failed to do so in gnotobiotic IL-10 knockout mice." (PMID 34386004, 2021). "STAT3 phosphorylation by IL-10, which is produced in a wide range of innate leukocytes (macrophages, neutrophils, and dendritic cells), might play a role in preventing the disease in experimental colitis models." (PMID 34068714, 2021). "IL-10-secreting neutrophils might induce immunosuppression under certain conditions and aggravate colitis by enhancing colonic bacterial invasion, suggesting a potentially important role for TRAF2-mediated TNF-α signaling in regulating IL-10-mediated colonic homeostasis." (PMID 34956195, 2021). "In humans, inhibition of IL-10 could cause the early IBD and more severe colitis." (PMID 34867926, 2021). "It was also found that macrophage-selective deletion of IL-10Rα (IL-10Rα model) markedly intensified DSS-induced colitis and increased pro-inflammatory cytokine production, thus, regulating the macrophage-derived IL-10 by EA was speculated to be an upstream modulator of macrophage polarization." (PMID 34281592, 2021). "In addition, IL-10 is necessary for induction and maintenance of Treg cells against colitis mice." (PMID 34867926, 2021). "Notably, IL-10 administration have proven efficacy in suppressing colitis in mice." (PMID 34249002, 2021). "In particular, Treg cells secreting anti-inflammatory cytokine IL-10 have been shown to partially prevent the development of the disease, while the disruption of IL-10 expression in Treg cells, residing in the intestinal mucosa, led to the development of spontaneous colitis in mice." (PMID 34163468, 2021). "To determine whether overexpression of SMILE affects effector T-cell populations, we examined the number of Th17 and Treg cells as well as IL-17-producing and IL-10-producing B cells in the MLNs of DSS-induced colitis mice treated with SMILE or mock vector by flow cytometry." (PMID 34211461, 2021). "Importantly, in the absence of IL-10, mice spontaneously develop colitis, and in humans, mutations in the IL-10 pathway are associated with the development of severe early-onset CD." (PMID 34360736, 2021). "We were encouraged to see our phenotype was consistent with that of the recently published germline IL-10–deficient animals and that colitis was likely not a factor underlying the weight loss and IR we observed in the Treg-specific IL-10– and Blimp-1–deficient animals." (PMID 33351782, 2021). "Similarly, induction of HO-1 in IL10-/- mice reduced development of colitis." (PMID 33803793, 2021). "In addition, mice with DSS-induced colitis exhibited a significant decrease in IL-10 in the serum." (PMID 34867926, 2021). "Indeed, the gut colonization by A. muciniphila aggravates colitis in Il10−/− mice." (PMID 34705319, 2021). "Moreover, oral cinnamon extract treatment caused a downregulation of tryptase and carboxypeptidase A3 (MC-CPA) expression and reduced expression of mast cell proteases (MC-CPA, MCP-1 and MCP-4) and pro-inflammatory mediators (CXCL8, CCL2, CCL3 and CCL4) during colitis in IL-10 knockout mice." (PMID 32962285, 2020).
colitis (continued). "Upregulated expression of IL-10 and Treg cells by human umbilical cord-derived MSCs has been associated with increased activation of the NOD2-RIP2 pathway and prolonged production of PGE2, which also inhibits the proliferation of mononuclear cells to attenuate colitis." (PMID 32256612, 2020). "Indeed, iRhom2-/-/IL10-/- mice develop a more severe spontaneous colitis than IL10-/- mice alone." (PMID 33585287, 2020). "Colitis is characterized by expression of both pro-inflammatory cytokines, including tumour necrosis factor-alpha (Tnfa), interleukin 1-β (Il1b), and interleukin 17 A (Il17a), and anti-inflammatory cytokines, including interleukin 10 (Il10) and interleukin 22 (Il22)." (PMID 32042047, 2020). "Likewise, we demonstrated that the relative composition of a defined group of human IBD-relevant bacterial strains evolved as colitis progressed in selectively colonized gnotobiotic Il10−/− mice in contrast to stable profiles of the same strains in identically colonized wild-type mice." (PMID 31482438, 2020). "However, the exact role of A. muciniphila in colitis remains to be confirmed, as colonization with this gram-negative species has also been shown to increase intestinal inflammation in both specific-pathogen-free and germ-free Il10−/− mice." (PMID 33162890, 2020). "Similarly, GF IL-10 deficient mice fail to develop colitis, unlike IL-2 deficient GF mice that exhibit spontaneous colitis when colonized with E. coli, but not Bacteroides vulgatus or both bacterial species together." (PMID 33147801, 2020). "Interestingly, while inulin has been demonstrated to have positive effects on inflammation in select situations, a number of studies have also suggested inulin can exacerbate the severity of colitis in an IL10−/− and DSS-model of colitis, and promote HCC-progression in mice." (PMID 33520902, 2020). "However, butyrate supplementation did not protect Il22−/− mice from DSS-induced colitis, although butyrate treatment in vivo increased both IL-22 and IL-10 production in mice, which suggests that butyrate induction of IL-10 alone is insufficient to decrease colitis severity in this model." (PMID 32901017, 2020). "We then reasoned that Cj-P1-DCA-Anaero might induce less colitis in Il10−/− mice compared to Cj-P1." (PMID 33257743, 2020). "Additionally, we investigated whether PRCC-1301 EVs alleviate DSS-induced colitis and chronic colitis in IL-10-/- models and protect the epithelial barrier in Caco-2 cells." (PMID 33233771, 2020). "And LP-YS4 could inhibit the colitis and reduce the secretion of IL-10." (PMID 32849906, 2020). "This lack of phenotype may be due to the relative cleanliness of our specific pathogen-free environment, which we have also shown to be sufficient to prevent the development of colitis in mice deficient in Il10-/- alone, in the absence of specific triggering." (PMID 32941525, 2020). "However, it has also been shown that iNKT cells contribute to intestinal homeostasis by interacting with CD1d-expressing, IL10 producing, epithelial cells and that iNKT cells protect mice from experimental colitis, albeit in IBD patients a protective role for iNKT cells has not been proven yet." (PMID 32429359, 2020). "Therefore, to investigate whether human MSCs improved inflammation-related diseases via increasing IL-10 producing Bregs, we employed the murine colitis model, which has been widely used to evaluate the immunomodulatory properties of human MSCs 54-56." (PMID 31367246, 2019). "Other chemicals such as TNBS or DSS could induce colitis in IL-10-/- or FVB mice." (PMID 31534535, 2019). "Furthermore, Helicobacter hepaticus and Lactobacillus reuteri do not induce disease in monoassociated IL-10−/− mice, but when both strains are used in a dual-association setup they induce severe colitis." (PMID 31281321, 2019).
colitis (continued). "The results showed that quercetin alleviated the effects of C. rodentium-induced colitis, suppressed the production of pro-inflammatory cytokines, such as interleukin (IL)-17, tumor necrosis factor alpha, and IL-6 (p < 0.05), and promoted the production of IL-10 in the colon tissues (p < 0.05)." (PMID 31156598, 2019). "However, a recent study indicated that ERβ signaling may only protect females from colitis and males benefit the activation of ERα instead, as the experiment in which ERβ antibody promoted IL-10 production was only carried out in cells isolated from females." (PMID 31226730, 2019). "In another model of CRC induced by application of AOM to colitis-susceptible Il10−/− mice lacking the immunoregulatory cytokine IL10, commensal polyketide synthase (pks)-positive E. coli were found to accelerate progression from dysplasia to invasive carcinoma." (PMID 31289620, 2019). "In this study, we also tested whether DSS could induce a sustained colitis in IL-10-/- mice." (PMID 31534535, 2019). "Hence, we next immunized IL-10 KO mice subjected to flagellin treatment weekly from 4–14 weeks of age, and thereafter, examined the extent to which such flagellin immunization impacted their development of colitis." (PMID 31827095, 2019). "In the TNBS model of colitis, Blend 2 reduced the expression of pro-inflammatory genes while increasing the production of anti-inflammatory cytokines, promoting the expansion M2 macrophages and the formation of IL-10-producing Treg cells in the colon’s lamina propria." (PMID 30717413, 2019). "Thus, in this study we analyzed whether distinct minimal bacterial consortia influence the outcome of MNV-triggered colitis in Il10−/− mice." (PMID 31396223, 2019). "Importantly, IL-10 plays a key role in regulating the pro-inflammatory responses of murine and human intestinal macrophages and mutations in its receptor, IL-10R, result in acute IBD in humans and severe spontaneous colitis in mice." (PMID 29559912, 2018). "Besides, BB and BBR also decreased the levels of IL-10 in DSS-treated colitis mice (P < 0.05)." (PMID 29538417, 2018). "Indeed, IL-10 appears to act primarily on macrophages to prevent the development of colitis." (PMID 30410494, 2018). "Thus, it is tempting to think that ERC may induce the production of IL-10-producing B cells, which results in and from the expansion of Tregs to form a complex loop to regulate the gut homeostasis and suppress colitis." (PMID 29784012, 2018). "Notably, we did not detect any signs of ME leukocyte infiltration in naïve ME, confirming that IL-10 deficient mice, known to spontaneously develop colitis at a certain age, exhibit no basal inflammation in the ME." (PMID 30581430, 2018). "Defective macrophage differentiation and IL-10-dependent STAT3 phosphorylation in DOCK8-deficient macrophages further strengthens our conclusion that WASP, together with DOCK8, regulates anti-inflammatory macrophage function and protects from colitis development." (PMID 29725003, 2018). "In addition, the administration of apelin to Il10−/− mice with established colitis resulted not only in an amelioration of disease by lowering the production of pro-inflammatory cytokines such as TNFα, IL-6, and IL-1β but furthermore enhanced intestinal lymphatic function." (PMID 30369924, 2018). "Thus, we next investigated whether IL-10 ameliorated DSS-induced colitis by restricting the monocyte/macrophage response." (PMID 29545807, 2018). "Thus, Th1 cells may not only serve as an inducer of colitis but also serve as a brake for colitis progression once IL-10 is produced." (PMID 30177845, 2018). "Thus, mice deficient in the antiinflammatory cytokine IL-10 (IL-10−/−) spontaneously develop a mild, patchy form of colitis which is highly dependent on the composition of the gut microbiota, given that the commensal Akkermansia muciniphila is able to induce colitis in IL-10−/− mice." (PMID 29213271, 2017).
colitis (continued). "In addition, we further perform IL-10-/- mice to clarify whether the BF through TLR2 /IL-10 pathway to alleviate DSS-colitis." (PMID 28683149, 2017). "Mechanistically, induction of IL-10 has been a recurrent theme in analyses of cytokine levels in helminth-infected mice alongside a generalized switch from Th1 to Th2 cytokine production, while the helminth-induced expansion of Tregs that suppress colitis has also been demonstrated." (PMID 28302598, 2017). "In the murine colitis model and other experimental settings, MSCs were shown to directly inhibit the antigen-presenting function of dendritic cells and macrophages, rendering them toward tolerogenic phenotype with increased IL-10 secretion and favored Treg induction." (PMID 28402942, 2017). "We showed that our nine-miRNA signature could discriminate between the different forms of colitis and arthritis, as well as between non-colitic mice with and without a genetic predisposition to develop the disease (WT mice versus non-colitic IL10−/− mice)." (PMID 28566745, 2017). "Thus, the anti-TNFα antibody efficiently diminished colitis in the IL10−/− mouse model." (PMID 28566745, 2017). "Since IL-10 is an important cytokine for gut homeostasis, its upregulation may help to control local inflammatory events and to prevent the outburst of a spontaneous colitis." (PMID 29209321, 2017). "Thus, the IL-10 pathway is partially necessary for the Hsp65-LL immunomodulatory effect in the spontaneous colitis suggesting that other mechanisms, such as the production of TGF-β1, may also be involved." (PMID 28194152, 2017). "Moreover VSL#3 application could ameliorate recurrent Th1-mediated TNBS colitis in mice by inducing IL-10 and IL-10-dependent regulatory T cells expressing TGF-β." (PMID 28413453, 2017). "Therefore, we consider modifying dysbiosis and enriching biodiversity might be important mechanisms in sodium butyrate amelioration of colitis in IL-10−/− mice." (PMID 27886121, 2016). "Plasma levels of IL-1β, IL-6, IL-10, IL-17, TNFα, and IFNγ were detected in blood samples from all experimental mice group at two different time points, one corresponding to the acute phase of colitis (day 25), and one at the end of the recovery phase (day 37)." (PMID 26973525, 2016). "As our IVC unit was free of Helicobacter hepaticus, which has been directly linked to the induction of large intestinal inflammation in SPF Il10−/− mice, we assessed whether IL-10–mediated control of CD11c+ cells was required to suppress Helicobacter hepaticus-elicited colitis." (PMID 27027442, 2016). "Interestingly, A. parvulum mono-associated GF Il10−/− mice did not cause significant colitis compared with controls suggesting that this bacterium cannot induce disease on its own (Histological score: 1.6 versus 0.67 respectively; not significant)." (PMID 27876802, 2016). "Also, IL-10 KO Treg-of-B cells protected against colitis to a similar extent as WT Treg-of-B cells." (PMID 27581189, 2016). "Indeed, C. rodentium infection induces a robust Th1/Th17 response with increased gene expression of IFN-γ, interleukin-12 (IL-12), IL-17, and IL-22 while acute DSS colitis activates a predominant Th1 response but with upregulation of several Th2 cytokines including IL-10." (PMID 27046199, 2016). "Thus S. mansoni soluble egg antigen (SEA) or cercariae exposure were shown to significantly attenuate trinitrobenzene sulfonic acid (TNBS)-induced or DSS-induced colitis in mice by enhancing IL-4 and IL-10 expression, decreasing INF-γ levels, or through induction of F4/80+ macrophages." (PMID 25879741, 2015). "An example of this hypothesis encompasses monoassociation of IL-10−/− mice with H. hepaticus or Lactobacillus reuteri, which as single strain did not induce inflammation, while the combination of the two bacteria induced colitis." (PMID 26635787, 2015). "Furthermore, ASC treatment increases expression of IL-10, which might enhance T-reg function, in mice with experimental colitis." (PMID 26210906, 2015).